STAT3 (signal transducer and activator of transcription 3)
Diseases named in the same sentence as STAT3 in open-access papers (continued):
Sharing a sentence is not in itself a finding about the gene and the disease.
tumor (continued). "IL-6 via STAT-3 has been shown to promote tumor cell proliferation in many cancers, including oral squamous cell carcinoma via DNA hypomethylation, prostate cancer through androgen receptor activation, and colon cancer." (PMID 34307156, 2021). "Although STAT3 and phosphorylated STAT3 activate telomerase in tumor cells, it still can play a positive role in aging and repair nerve injury." (PMID 34262731, 2021). "The results obtained show that the codelivery of STAT3 siRNA and IM using AuNPs showed a significant (p < 0.05) reduction in percentage tumor volume, tumor weight and suppressed STAT3 protein expression." (PMID 34207175, 2021). "On one hand, tumor-infiltrating B cells can secrete lymphotoxin, which induces angiogenesis, and activates NF-κB signaling and STAT3 in the cancer cells thereby promoting tumor growth." (PMID 33494389, 2021). "STAT3 hyperactivation in tumor cells can occur as a result of increased IL-6 levels in the serum and/or the tumor microenvironment, or as a result of loss-of-function mutations affecting STAT3 negative regulators." (PMID 35155571, 2021). "Our result is supported by preclinical studies which revealed that aberrant STAT3 expression mediates immunosuppression of tumor cells." (PMID 33668805, 2021). "JAK2/STAT3 is considered a key signaling molecular pathway that promotes tumor cell growth and progression and participates in tumor metastasis by targeting molecular signals that regulate many of the cancer hallmarks." (PMID 34576006, 2021). "Tumor progression was monitored following treatment with vehicle, the small molecule STAT3 inhibitor GPB730, anti-CTLA-4 or GPB730 + anti-CTLA-4." (PMID 33786638, 2021). "Transient STAT3 activation mediates wound healing and tissue integrity and persistent STAT3 activation promotes tumor cell proliferation, survival, invasion, and immunosuppression." (PMID 33594990, 2021). "S1PR1‐5 are largely regarded as protumorigenic receptors as they can activate numerous tumor‐associated signaling pathways, such as the Ras/ERK, PI3K/Akt, STAT3, and PLC pathways." (PMID 34766135, 2021). "We found that CDK2, CDK4, CDK6, and STAT3 expressions were higher in tumor cohorts compared to normal cohorts." (PMID 33668805, 2021). "Intrinsic STAT3 activity in CAFs has emerged as a mechanism by which CAFs support tumor progression." (PMID 34858425, 2021). "Inhibition of STAT3 signalling decreases the expression of genes that provide the tumour a growth advantage as well as suppressing the effects coming from cells in the microenvironment." (PMID 33274592, 2021). "A JAK2/STAT3 signaling pathway has been previously found activated abnormally in varieties of tumor tissues, which exerts great impact on tumor progression." (PMID 34663387, 2021). "Several anti-apoptotic proteins, such as Survivin and members of the Bcl family (Bcl-XL, Bcl-2, and Mcl-1), which are essential for tumor cell survival, are direct target genes of STAT3 and downregulated as a consequence of STAT3 inhibition." (PMID 34638708, 2021). "Herb-derived natural products, interfering with STAT3 signaling in tumor cells, are promising therapeutic agents in cancer treatment." (PMID 34884773, 2021). "The JAK/STAT3 pathway is aberrantly activated in various cancers, including OC, and is involved in functional regulation of the tumor microenvironment." (PMID 34041016, 2021). "On the contrary, M2 cells are activated by type II cytokines such as IL-4, IL-10, IL-13, and transforming growth factor (TGF)-β, performing a pro-tumor immune response by producing factors as STAT3, which contribute to tumor proliferation." (PMID 33917013, 2021). "STAT3 knockout can enhance the inhibitory effect of anthracycline-based chemotherapies on tumor cells." (PMID 34926570, 2021).
tumor (continued). "Inhibition of STAT3 was found to induce cytotoxic T lymphocyte activation and the resultant anti-tumor immune responses." (PMID 34439380, 2021). "Interleukin-6 (IL-6) is a typical tumor promoting cytokine in the interleukin-6 cytokine family, which regulates various STAT3-mediated carcinogenesis." (PMID 34384424, 2021). "For this reason, pharmacological inhibition of JAK/STAT3 with NHWD-870 appears to be a promising strategy for the treatment of bone-associated tumors, as it disturbs the vicious cycle between tumor progression and bone remodeling." (PMID 34168981, 2021). "One important transcription factor in this process is STAT3 known to play a key role in liver fibrosis and tumor progression." (PMID 34638417, 2021). "Another mechanism of tumor promotion is linked to the interaction between HCV core proteins and STAT3 protein, a molecule involved in the regulation of cytokine signaling." (PMID 33513730, 2021). "A recent work stratified GBM patients into Stat3-high and Stat3-low cohorts and showed that Stat3 inhibitors were effective in reducing Stat3-high tumor cell viability and tumorigenicity in mouse xenograft models." (PMID 34376733, 2021). "It is important to mention that STAT3 is an essential transcription factor that affects a wide variety of cell-intrinsic and extrinsic signaling pathways that together contribute to tumor cell proliferation and metastasis." (PMID 33235291, 2021). "A previous study illustrated that the crosstalk between JAK1/STAT3 and NF‐kB is central for tumor progression." (PMID 33634982, 2021). "Unexpectedly, genetic inactivation of STAT3 or IL-6 in prostate-specific PTEN knock-out mice led to accelerated tumour progression and metastasis." (PMID 34047814, 2021). "Viral interleukin-6 promotes cell proliferation, tumor invasion, and angiogenesis by suppressing caveolin 1, which plays a role in tumor development mediated by DNA methyltransferase 1 (DNMT1)-targeted STAT3 acetylation." (PMID 35008848, 2021). "The STAT3 signaling pathway is involved in the induction and function of immunosuppressive cells and the inhibition of dendritic cell functions in the tumor microenvironment, thus promoting immune evasion in cancer." (PMID 33786638, 2021). "Overall, these results suggest that STAT3 plays an immunosuppressive role in the tumor microenvironment." (PMID 32483429, 2020). "Primary tumor-secreted IL-6 activated STAT3 in lymphatic endothelial cells, which then induced the expression of hypoxia-inducible factor 1 (HIF-1), vascular endothelial growth factor (VEGF), and chemokine ligand 5 (CCL5)." (PMID 33322216, 2020). "Previous work found that IL-10, an immunosuppressive cytokine that enhances the tumor-supporting functions of macrophages, induces lipocalin-2 expression in macrophages via activation of the Jak/Stat3 signaling pathway." (PMID 33679721, 2020). "Persistent STAT3 signaling leads to uncontrolled nuclear gene expression, which results in the growth and survival of tumor cells." (PMID 32714202, 2020). "IL-17+ and IL-22+ which are involved in both wound healing and tumor development through activation of STAT3." (PMID 32100077, 2020). "RhoA expression is also elevated in CRC tumour samples, which results in increased pTyr705 STAT3 and increased CRC cell migration." (PMID 32915198, 2020). "The increase in CD45 tyrosine phosphatase activity in the hypoxic environment of the tumor promotes the downregulation of STAT3 expression, thereby promoting the differentiation of M-MDSCs into TAMs." (PMID 32005273, 2020). "A decoy oligonucleotide targeting STAT3 offers a promising anti-tumor strategy, but achieving targeted tumor delivery of the decoy with systemic administration poses a significant challenge." (PMID 33206698, 2020).
tumor (continued). "It has been reported that intracellular IL-37b can interact with Smad3 to suppress multiple signaling pathways (such as ERK, p38 MAPK, JNK, PI3K, NF-κB, and STAT3 pathways) and modulate the expression of metastasis-related genes in tumor cells." (PMID 32226541, 2020). "Cytokine IL-6, a major mediator of inflammation and activator of STAT3, serves to block apoptosis and promote tumor survival." (PMID 32576206, 2020). "Particularly, widely known for its role in proliferation, apoptosis, angiogenesis and invasion of cancer cells, constitutively activated JAK/STAT3 pathway accelerates tumour progression in diverse cancer types." (PMID 32285621, 2020). "We also studied an HPV associated experimental model to better understand the potential effects of blocking STAT3, one of the signaling proteins investigated, on tumor growth and anti-tumor immune responses." (PMID 33330068, 2020). "We found that HJC0152 exhibited activity against human NSCLC cells in vitro and NSCLC xenograft tumours in vivo via regulating STAT3 signalling and metabolism." (PMID 32022328, 2020). "Western blotting also showed that p‐STAT3 expression levels were lower in the tumours injected with IGF2BP3 depleted cells than that in the vector‐transfected cells." (PMID 33094561, 2020). "In the tumor microenvironment, IL6/JAK/STAT3 signaling drives proliferation, survival, invasiveness, and metastasis of tumor cells, while strongly suppressing the anti-tumor immune response." (PMID 32957689, 2020). "Studies using pharmacological approaches, siRNA technology, Mx1-Cre, CD4-Cre or Ncr1-iCreTg mice to abrogate STAT3 signaling in immune cells further confirmed that STAT3 impairs anti-tumor immunity." (PMID 32365499, 2020). "Below, we discuss potential roles for CD44 and STAT3 in different aspects of metabolism switch in cancer cells that support tumor progression." (PMID 33335857, 2020). "Our research found that the phosphorylation level of STAT3 increased significantly when tumor cells lost PTEN and decreased when PTEN levels increased." (PMID 32471980, 2020). "STAT3 is required for tumor formation and maintenance of the self-renewal of GBM stem-like cells, some of which express CD133 as a cancer stem cell marker." (PMID 31963897, 2020). "In vivo experiments showed that miR-126 knock-down inhibited ESCC tumor growth in mice and inhibited the expression of STAT3, an essential oncogene and therapeutic target." (PMID 32554852, 2020). "A similar finding was observed in tumor-associated macrophages, in which IL-4 synergized with IL-10 to activate the UPR via STAT3." (PMID 32714202, 2020). "Colonic epithelial cells expressing HPSE and mucosal macrophages interacted to maintain a chronic inflammatory condition, which aided the formation of a tumour-promoting microenvironment with NF-κB signalling and induction of STAT3 expression." (PMID 33256730, 2020). "It mainly acts as an inhibitor of cellular processes via regulation of transcription factors NF-κB and JAK/STAT3 in tumor cells and have been demonstrated to effectively inhibit growth of malignant cell population." (PMID 32365899, 2020). "Owing to the recent advancement in bioinformatics, we aim to reveal the impact of STAT3 in tumor immune microenvironment and drug response comprehensively by bioinformatics analysis." (PMID 32486001, 2020). "Activation of STAT3 is reported to upregulate immunosuppressive cytokines to promote tumor immune evasion." (PMID 32312954, 2020). "In this respect, it is noteworthy that Rg3 represses STAT3 phosphorylation in tumor cells by decreasing the hexokinase 2 level." (PMID 31936879, 2020). "In our mouse tumor model, STAT3 inhibition led to an increase in phoshorylated-p65-NFκB expression, both in the tumor as in the spleen." (PMID 33330068, 2020).
tumor (continued). "In pre-clinical studies in lung and lymphoma cancer cells, AZD9150, which is more stable than previous iterations due to a different scaffold, decreased STAT3 expression and demonstrated significant anti-tumour activity." (PMID 32899142, 2020). "IL-1β is known to influence apoptosis of tumor cells via induction of STAT3 Concordantly, we found a tendency towards up-regulation of STAT3 and decreased apoptosis rates in GBM cells after IL-1β treatment." (PMID 32069807, 2020). "Evidence from the literature indicate that Stat3 is activated by epidermal growth factor receptor (EGFR) stress-exposed tumor cells and is associated with a survival advantage for tumor cells (reviewed in Balanis and Carlin)." (PMID 32722178, 2020). "Our findings indicate that miR-125b acts as a tumor suppressor in CSCC by targeting the STAT3 pathway." (PMID 32161621, 2020). "The signal transducers and activators of transcription 3 (STAT3) is constitutively activated in diverse tumors and also involved in tumor growth 6-8." (PMID 31929760, 2020). "Overall, the overexpression of STAT3 provides the poor prognosis of patients with GC and its expression undergoes upregulation at the point when the gastric mucosa reaches the tumor stage." (PMID 32545648, 2020). "Our results shed light on the potential role of STAT3 in mediating the immune response in the tumor microenvironment." (PMID 32486001, 2020). "Given that immature DCs cannot activate antigen-specific CD8+ T cells, activated STAT3 signaling in tumor cells reduces the anti-tumorigenic effector functions of CD8+ T cells." (PMID 32972405, 2020). "On the other hand, many studies have reported that STAT3 also inhibits cell proliferation, for instance, in mediating breast degeneration and inhibiting proliferation in certain tumor types." (PMID 32714202, 2020). "JAK2/STAT3 pathway inhibitors can prolong the survival of mice by slowing tumor growth and stromal modification, in addition to altering immune cell infiltration." (PMID 33029256, 2020). "All together, these results suggested that GCAFs promote VM formation and tumor growth in GBC via upregulating NOX4 expression through paracrine IL-6 mediating IL-6/JAK/STAT3 signaling pathway." (PMID 33153467, 2020). "Collectively, these studies substantiate the previously suggested notion that STAT3 exerts two opposing roles in tumorigenesis depending on the cellular context and/or on the tumor genetic driver." (PMID 32365499, 2020). "Meanwhile, we detected that Stat3 was drastically activated only in tumor cells treated by IL-6-CM, and addition PP VII prior IL-6 in macrophages during preparing CM prevented the provocation, but not for STING-knockdown macrophages." (PMID 33288772, 2020). "Among the gankyrin-interacting proteins, STAT3, which serves as a transcription factor in tumor progression, was significantly expressed." (PMID 32051393, 2020). "The signal transducer and activator of transcription-3 (STAT3) has been reported to play a pivotal role in maintaining the tumour initiating capacity of the GSC population." (PMID 32486489, 2020). "Through all these pre-clinical studies, we can conclude that IL-6 is a potent inflammatory cytokines and activator of STAT3, produced not only by tumor cells but also by cells in the PMN." (PMID 33322216, 2020). "Significant differences (p<0.05) in tumor volumes were observed between the STAT3-MB + UTMC group and the two control groups starting at Day 3 and continuing until the end of study period." (PMID 33206698, 2020). "STAT3, as a transcription factor, is identified as a positive oncogene participating in tumor advancement which activation inhibits apoptosis through the cell cycle, aerobic glycolysis, metastasis." (PMID 32127943, 2020).
tumor (continued). "The C/EBPδ gene promoter can be activated by the STAT3 transcription factor, which is frequently hyperactivated in cancer and is a well-characterized tumor-promoting factor." (PMID 32560326, 2020). "Persistent activation of STAT3 in various tumor types makes STAT3 a specific and promising target in anticancer treatment." (PMID 32733808, 2020). "Within tumor microenvironments, IL-6/JAK/STAT3 signaling contributes to growth and metastasis of tumor cells by inhibiting the anti-tumor immune response." (PMID 32420905, 2020). "Polarization of the Treg phenotype in tumor tissue seems to be strictly dependent on activation of STAT3." (PMID 32488850, 2020). "Consistently, STAT3 phosphorylation was increased to a greater extent in skeletal muscle of mHCT116 tumor hosts relative to all other groups, including the subcutaneous HCT116 hosts." (PMID 31915140, 2020). "CD44 and STAT3 cooperate at multiple levels in both malignant and the normal cells in the tumor microenvironment, leading to cancer progression and resistance to therapies." (PMID 33335857, 2020). "Although the inhibitors of STAT3 have been studied and proven to be efficient in preclinic for 20 years, they showed poor anti-tumor effect in clinical trials." (PMID 32733808, 2020). "The oncogenic activity of mitochondrial STAT3 was first demonstrated in H-RasV12-transformed cells where it promotes anchorage-independent cell growth and tumor induction in mice." (PMID 31963765, 2020). "As a point of convergence for numerous oncogenic signaling pathways, signal transducer and activator of transcription 3 (STAT3) is central in regulating the anti-tumor immune response." (PMID 32972405, 2020). "Tumor cells interact with microglia and affect angiogenesis and survival through activation of STAT3 pathway in microglia." (PMID 33537237, 2020). "Although STAT3 signaling is linked to various regulatory events causing increased proliferation, stemness, and inflammation and therefore has oncogenic properties, STAT3 can also act as tumor suppressor." (PMID 32323921, 2020). "Complementing these levels of IL-6/STAT3-driven pro-tumor activities in BC is the aspect of endocrine resistance." (PMID 32605277, 2020). "Decreased expression of STAT3 and a concomitant downregulation of p-STAT3 were observed in tumor tissues derived from miR-125b-5p-overexpressing Tsc1-/- MEFs compared to the corresponding control cells." (PMID 31949495, 2020). "The high level of STAT3 and pSTAT3 is closely related to the tumor progression and poor prognosis of cancer patients." (PMID 32943090, 2020). "The activity of mitochondrial STAT3 in tumor tissues is suggested to be dependent on STAT3 phosphorylation at Ser727." (PMID 33003453, 2020). "From Jean’s work, IL-6 and interferon pathways were activated in GNAS-mutated tumor tissues, suggesting that GNAS enzymatic activity is necessary for IL-6/STAT3 activation." (PMID 32123532, 2020). "The activation of fundamental components of cellular metabolism and DNA methylation involves tumor progression by regulation of STAT3 activity." (PMID 31952344, 2020). "IL-6/STAT3 signaling in tumor-containing lung tissue is activated via reciprocal interactions between metastatic tumor cells and stromal cells." (PMID 33322216, 2020). "Several preclinical studies have demonstrated that inhibiting STAT3 activation resulted in reduced cell growth and increased apoptosis in tumor cells." (PMID 33536913, 2020). "WCAF treatment decreased the mRNA expression of Leptin and VEGF-A, while the protein levels of CD31, LEP-R, VEGFR-1, STAT3, and p-STAT3 were decreased in tumor tissues." (PMID 33746736, 2020). "Recent reports demonstrated that Docetaxel promoted MDSCs differentiation into M1-like macrophages with anti-tumor activity by reducing the phosphorylation levels of STAT3 in 4T1 breast tumor-bearing mice." (PMID 33613512, 2020). "The expression of STAT3 in tumor correlated with the increased angiogenesis in ABC group of patients." (PMID 32731512, 2020).